NRAS (NRAS proto-oncogene, GTPase)
Diseases named in the same sentence as NRAS in open-access papers (continued):
Sharing a sentence is not in itself a finding about the gene and the disease.
cancer (continued). "Taken together, these findings suggest that the oncogenic role of the circPVT1/let-7/NRAS axis may be found across different cancer types, representing a more general mechanism of noncoding RNA-modulated oncogenicity." (PMID 33907219, 2021). "In mice, the deletion of KRAS has been found to be more lethal than the deletion of NRAS and HRAS; therefore, the use of mutant allele-specific inhibitors in humans was proposed to be a more targeted, viable approach for treating RAS mutant cancers." (PMID 34830283, 2021). "Several cancer-associated genes—Fibroblast Growth Factor Receptor-3 (FGFR3), phosphatidylinositol-4,5-bisphosphate 3-kinase catalytic subunit alpha (PIK3CA) and N-ras proto-oncogene (NRAS) are identified as mutant in HT1197 when compared to HT137642." (PMID 33790357, 2021). "The MAPK pathway is commonly activated in cancers by driver mutations in KRAS, NRAS, and BRAF." (PMID 34214079, 2021). "The HRAS, NRAS, and KRAS genes are collectively mutated in a fifth of all human cancers." (PMID 34504076, 2021). "NRAS (N-ras), a member of the RAS family, and commonly mutated in almost all human cancers." (PMID 34671612, 2021). "The KRAS, NRAS and HRAS oncogenes are mutated in approximately 30% of all human cancers." (PMID 33924486, 2021). "The four cancer cell lines examined, harboring BRAF or NRAS mutations, were susceptible to LT." (PMID 34064422, 2021). "Lesions classified as intermediate by histopathological characteristics and melanomas in situ harbor a broader spectrum of oncogenic alterations, including BRAFV600K or BRAFK601E, NRAS, GNAQ or GNA11, and TERTprom mutations, showing genetic differences between benign and malignant neoplasms." (PMID 34123788, 2021). "Additionally, the scientific literature commonly estimates 30–33% of all cancers have a mutation in either KRAS, NRAS, or HRAS50–52." (PMID 34645806, 2021). "Numerous somatic mutations, including cancer-associated mutations in ARID1A, ATM, CDH4, NRAS, and PIK3CA, were shared among the epithelium from the uterine endometrium, endometriotic lesions distant from and adjacent to the carcinoma, and the carcinoma itself." (PMID 33809880, 2021). "It is known that NRAS‐mutant cancer cell lines rely on signalling through CRAF (RAF1) and SHOC2 and we could identify this association as a highly significant association in CEN‐tools." (PMID 33073517, 2020). "RAS mutations in all cancer types occur mostly in KRAS (85%), followed by NRAS (12%) and HRAS (3%)." (PMID 31941155, 2020). "While the majority of Class 1 (RAF dependent) MAP2K1 mutations are associated with co-mutation in BRAF, NRAS, or NF1, only a small proportion of class 2 (RAF regulated) cases and no class 3 (RAF regulated) cases share these co-mutations in a limited pan-cancer analysis." (PMID 32483240, 2020).
cancer (continued). "Based on these last observations, several natural compound libraries were screened using a phosphorylation assay-based approach and chelidonine was identified as a potent and selective inhibitor of STK19, providing a novel option for targeting NRAS-mutant cancers." (PMID 32850962, 2020). "Hotspots, recurrently mutated DNA positions in cancer, are thought to be oncogenic drivers because random chance is unlikely and the knowledge of clear examples of oncogenic hotspots in genes like BRAF, IDH1, KRAS and NRAS among many other genes." (PMID 32386297, 2020). "Finally, mutations in the TERT promoter and NRAS, PTEN, and PIK3CA genes are occasional molecular drivers of cancer in the pediatric population." (PMID 31456750, 2019). "For instance, gain‐of‐function mutations and overexpression of RAS family members (KRAS, HRAS, and NRAS) are among the most prevalent oncogenic lesions in human cancers, and high levels of Ras activity are necessary to maintain the transformed phenotype in some Ras‐driven cancers." (PMID 30422399, 2019). "Interestingly, when a subsequent plasma analysis was performed at disease progression, the same NRAS mutation previously evidenced in NGS tissue testing at baseline (Q61H) was detected, suggesting cancer cell clonal expansion." (PMID 31597339, 2019). "To assess whether our filtering strategy retained known somatic mutations, we tested the impact of this strategy on the hotspot mutations in five known cancer-associated genes: BRAF, RAS family (HRAS, NRAS, and KRAS), and stop-gain NF1 gene mutations." (PMID 30662871, 2018). "Our studies identified NEK9 and CDK16 as two dabrafenib‐specific kinase targets and provide evidence that inhibition of NEK9 and CDK16 may underlie the greater effectiveness of this drug against NRAS‐ and KRAS‐mutant cancer cells." (PMID 29112787, 2018). "IL‐8‐related chemokines, NRAS signaling partners in this process, may constitute an important therapeutic target against pulmonary involvement by cancers of other organs." (PMID 28341702, 2017). "Also, while most early studies utilized the activated form of HRAS (generally referred to as RAS), each RAS isoform (HRAS, KRAS and NRAS) has a distinct biological function, and KRAS mutations are much more common in human cancers than NRAS and HRAS mutations." (PMID 28152508, 2017). "In sum, the findings of this retrospective polyps study combined with the novel CDH1 and NRAS germline mutations found in the CRC groups emphasize the existence of the Taiwanese-specific genome and provided candidate genes for cancer risk assessment in the general population." (PMID 29069792, 2017). "Interestingly, CXCR1 expression was largely restricted to the lung endothelium, and NRAS‐mutant cancer cells exhibited a specific pulmonary metastatic pattern likely dictated by their chemokine expression profile, similar to other pro‐metastatic axes." (PMID 28341702, 2017). "NRAS was previously identified as an oncogene in several cancers." (PMID 27556696, 2016). "NRAS mutations activate downstream kinases including RAF and MEK1/2 (MAP2K1/2), and preclinical and early clinical data showed that NRAS-mutant cell lines and tumors of cancer patients are highly sensitive to MEK1/2 inhibitors." (PMID 27613601, 2016). "We developed a novel mass spectrometry multiplexed genotyping platform named PentaPanel to concurrently assess single nucleotide polymorphisms in 56 hotspots of the 5 most clinically relevant cancer genes, KRAS, NRAS, BRAF, EGFR and PIK3CA for a total of 221 detectable mutations." (PMID 26435479, 2015). "In- and out-degree of BRAF and NRAS genes in TO-DAG network inferred from Cancer Genes list." (PMID 26528329, 2015). "Furthermore, our results are in line with NRAS knockdown experiments published previously, proving that NRAS is a bona fide oncogene in our subset of cancer cell lines." (PMID 25277205, 2014).
cancer (continued). "Low levels of let-7b and -c have been identified in different subtypes of AML, and the causal relationship of its deregulated expression in cancer can be supported by evidence suggesting it targets a number of genes involved in the cancer process such as KRAS, TRIM71, nRAS, MYC, and HMGA2." (PMID 24416592, 2013). "Binary classification is the process of classifying objects within a group (cancer patients) into two subsets, cancer patients with mutations in KRAS, BRAF or NRAS, and cancer patients without mutations in these genes." (PMID 23991070, 2013). "This immunological phenotype may help to understand the importance of NRAS in hematopoiesis and oncogenesis and add to the discussion on whether NRAS can act as initiator of abnormal cell growth eventually leading to cancer." (PMID 22876308, 2012). "However, constitutive activating mutations in signaling components downstream of EGFR, like NRAS(Q61L) or BRAF(V600E), are common in cancer cells." (PMID 22253908, 2012). "Ras has many isoforms of which NRas and KRas are the most relevant to human cancer." (PMID 21479172, 2011). "Therefore, we explored a treatment that can prevent cancer cells from producing the NRAS protein." (PMID 40473796, 2025). "However, mutations caused by NRAS, KRAS, BRAF, PI3KCA, and Akt activation in cancers may confer the cancer cells’ therapeutic resistance to cetuximab and render it a less effective anti-cancer agent." (PMID 37507626, 2024). "Furthermore, it was shown, that MALAT1 may act as master regulator of several protein-coding hub-genes in drug-resistant NRAS-mutant cancer." (PMID 37235843, 2023). "NRAS mutations have also been identified as resistance mechanisms using patient-derived cell line models harboring RET and ROS1 gene fusions, further supporting the idea that cancers often develop resistance using a somewhat finite group of oncogenes following TKI treatment." (PMID 34642436, 2021). "Thus, increased NRAS expression due to circPVT1 may enhance these phenotypes as well in cancer cells." (PMID 33907219, 2021). "Knockdown studies showed that the non-mutated WT RAS genes are necessary for growth-factor-mediated signaling to RAS effector pathways in HRAS-, NRAS, and KRAS-mutated cancer cells, indicating that cancer cell response to growth factors may be mediated by WT RAS, not the oncogenic RAS mutant." (PMID 33924994, 2021). "Thus far, high-throughput resequencing efforts worldwide aimed at identifying unknown somatic mutations in human cancer have already revealed that yet uncharacterized mutations in KRAS, NRAS, BRAF, PIK3CA, PTEN and other cancer genes are highly prevalent." (PMID 32620824, 2020). "Over 30% of cancers are driven by mutant Ras proteins, thereinto, one method called catalog of somatic mutations in cancer (COSMIC) confirms that HRas (3%) are the least frequently mutated Ras isoforms in human cancers, where KRas (86%) are the predominantly mutated isoforms followed by NRas (11%)." (PMID 33266473, 2020).
cancer (continued). "Although β-catenin- and RAS-destabilizing compounds induced the degradation of HRAS and NRAS, these could be beneficial for the treatment of cancer, because the overexpression of WT-HRAS or -NRAS is known to play roles in the promotion of MT-KRAS-driven tumorigenesis." (PMID 30459318, 2018). "While weighing the treatment options for these two cancers, although our initial thoughts were to focus on the more aggressive melanoma (BRAF and NRAS wild type), we were motivated to design a therapy regimen that could yield efficacious responses against both cancers." (PMID 27099755, 2016). "Mutations in RAS proto-oncogenes (comprising H-, N- and K-RAS) are among the most common in malignant tumours and although RAS isoforms are very similar, KRAS is more frequently found mutated in cancers occurring in 22% of all tumours analysed compared to 8% for NRAS and 3% for HRAS." (PMID 24720724, 2014). "Importantly, our findings suggest that the correlation between NRAS and BRAF mutations and their differential response to antifolate drugs might apply to other cancer types." (PMID 24941944, 2014). "Yet, cancers driven by oncogenic KRAS, HRAS, or NRAS remain strongly SHOC2-dependent, suggesting that these weaker complexes contribute to tumorigenesis." (PMID 41519889, 2026). "S7) there were many known and candidate “cancer genes” (again, of the Cancer Gene Census from COSMIC), including enhanced expression of NRAS, KMT2D, and CD74." (PMID 41187221, 2025). "As KRAS, NRAS, and HRAS are commonly altered genes in cancer, the pursuit of RAS inhibitors remains an active area of contemporary drug development research." (PMID 39858030, 2025). "FTase proteins (FNTA and FNTB) as well as eight of the 116 PFPs are known cancer-relevant proteins as per COSMIC Cancer Gene Census49 or TCGA50 (KRAS, HRAS, NRAS, RHEB, RHOA, DDX3X, ARID2, and SAV1)." (PMID 39995872, 2025). "In contrast to KRAS and NRAS, HRAS undergoes exclusively farnesylation through FTase, making FTIs potentially helpful in treating HRAS-mutant cancers." (PMID 40335986, 2025). "The observed downregulation of critical oncogenes such as KRAS, NRAS and MYC further highlights the potential of this combination therapy to target multiple oncogenic pathways, reducing the likelihood of cancer cell survival and proliferation." (PMID 40307570, 2025). "METTL13 knockdown inhibited B-ALL driver gene NRAS, and ERBB3, which is frequently overexpressed in cancer." (PMID 41282185, 2025). "KRAS, NRAS, and HRAS are the three main isoforms affected in cancer; among them, KRAS is the most frequent gain-of-function mutation, occurring in up to 90% of pancreatic cancer, 50% of colorectal cancer, and 30% of lung adenocarcinoma." (PMID 40970755, 2025). "Research indicates that ROS can influence tumorigenesis and cellular transformation by oxidizing cysteine residues, which subsequently activate the three most prevalent oncogenic switch genes in human cancers: HRAS, NRAS, and KRAS." (PMID 40181979, 2025). "Besides the well-known role of mutations in members of the MAPK pathways, such as BRAF and NRAS, an increasing number of studies have linked gene polymorphism and genetic variants to the members of the PI3K/AKT signaling pathway as susceptibility for cancer development." (PMID 40075679, 2025). "Rat sarcoma (RAS) proto-oncogenes play an important role in the development of cancer, with the three RAS genes (HRAS, NRAS and KRAS) being the most commonly activated drivers of cancer within this family." (PMID 40868227, 2025). "We found that PI3K-AKT signaling pathway was significantly inhibited in NRAS, KRAS, and HRAS mutant-cancer cell lines upon treatment with BAY 11-7082 as observed by reduced p-AKT protein level." (PMID 38982514, 2024).
cancer (continued). "We treated multiple NRAS (SKMEL-103, M245, and SKMEL-2), KRAS (AsPC1, PANC1, and SU.86.86), and HRAS (RH-36 and SMS-CTR) mutant cancer cell lines with different concentrations of BAY 11-7082 and measured cell viability." (PMID 38982514, 2024). "Among RAS mutant cancer cell lines, KRASG12X and NRAS glutamine 61 mutant (NRASQ61X) cells were significantly more sensitive compared with cell lines with other oncogenic KRAS or NRAS mutations, respectively (Wilcoxon rank-sum test with continuity correction)." (PMID 38593348, 2024). "We find that oncogenic NRAS, KRAS, and HRAS activate the expression of IkappaBalpha (IκBα) and BAY 11-7082, an inhibitor of IκBα kinase, attenuates the growth of NRAS, KRAS, and HRAS mutant cancer cells in cell culture and in vivo mouse model." (PMID 38982514, 2024). "It will provide a versatile solution to the genetic heterogeneity observed in different cancers harboring HRAS, NRAS, and KRAS, making it a valuable tool to treat various malignancies with RAS mutations." (PMID 38982514, 2024). "The most prevalent post-translational modification within the GTPase core domain of NRAS and KRAS is ubiquitination at lysine 128 (K128), which is significantly decreased in cancer samples compared to normal tissue." (PMID 38858602, 2024). "The RAS family proto-oncogenes (KRAS, NRAS, HRAS) play a crucial role in cellular signaling and cancer biology." (PMID 39001451, 2024). "We observed similar results, namely BAY 11-7082 treatment leads to significant increase in PARP-cleavage in NRAS, KRAS, and HRAS mutant-cancer cell lines." (PMID 38982514, 2024). "Three RAS proteins (HRAS, KRAS, NRAS; hereon H/K/NRAS or classical RAS) have been studied extensively, attributed to their role in oncogenesis and frequent activation in human cancers." (PMID 39009833, 2024). "BAY 11-7082, an inhibitor of IκBα kinase, attenuates the growth of NRAS, KRAS, and HRAS mutant cancer cells in cell culture and in mouse model." (PMID 38982514, 2024). "We next measured the apoptosis induction using annexin V and PI staining method and found a significant increase in apoptosis induction in NRAS, KRAS, and HRAS mutant-cancer cell lines upon treatment with BAY 11-7082 as compared to DMSO treated cells." (PMID 38982514, 2024). "KRAS-4B has been shown to be most expressed across a range of cancer cell lines and healthy mouse tissue, followed by KRAS-4A, NRAS and lastly HRAS." (PMID 39372214, 2024). "In our experiments, the only genes in which THCA is included as a held-out cancer type are BRAF and NRAS; generalization performance for both genes is below cross-validation performance but slightly worse for NRAS than BRAF." (PMID 39776849, 2024). "The RAS genes (KRAS, NRAS, HRAS) hold significant historical importance as they were the first human oncogenes discovered in the field of cancer research." (PMID 39455841, 2024). "This study shows that monoubiquitination of KRAS and NRAS at lysine 128 (K128) enhances RAS binding to GTPase-activating proteins to restrict RAS activity, a mechanism that is dysregulated in cancer tissues." (PMID 38858602, 2024). "An examination of CERES scores among KRAS, NRAS, and BRAFV600E mutant cancer cell lines indicated that KRAS and NRAS mutant cells had a heightened reliance on CRAF for proliferation, while BRAFV600E mutant cells primarily depended on BRAF for their growth." (PMID 38111008, 2023). "Among the three isoforms (KRAS, NRAS, and HRAS), Kirsten rat sarcoma viral oncogene homolog (KRAS) is the common oncogene in a large percentage of cancers, including pancreatic cancer, non-small cell lung cancer (NSCLC), and colorectal cancer." (PMID 37662925, 2023).